TBC1D14 (TBC1 domain family member 14)
Description:
Plays a role in the regulation of starvation-induced autophagosome formation. Together with the TRAPPIII complex, regulates a constitutive trafficking step from peripheral recycling endosomes to the early Golgi, maintaining the cycling pool of ATG9 required for initiation of autophagy.
Synonyms: KIAA1322
Tractability: PROTAC: ubiquitination databases record sites on it.
Gene: Protein-coding gene on chromosome 4 (6,909,242 to 7,033,118, forward strand). Ensembl gene ENSG00000132405.
Subcellular location: Golgi apparatus, cis-Golgi network; Golgi apparatus, trans-Golgi network
Subcellular location (Human Protein Atlas): Golgi apparatus; Vesicles; Nucleoplasm
Pathways (Reactome):
Vesicle-mediated transport: TBC/RABGAPs
Gene Ontology:
Molecular function: protein binding; protein kinase binding; GTPase activator activity; enzyme binding
Biological process: negative regulation of autophagy; recycling endosome to Golgi transport; regulation of autophagosome assembly; regulation of cilium assembly; vesicle-mediated transport
Cellular component: autophagosome; Golgi apparatus; recycling endosome; cytoplasmic vesicle; cytosol; vacuole
Genetic constraint (gnomAD): Loss-of-function variants: 22 observed, 72.71 expected, observed/expected ratio (o/e) 0.3, 90% interval 0.22 to 0.43. The upper end of that interval is the gene's LOEUF score, 0.43, which puts it in group 1 of 6, group 1 being the genes least tolerant of losing a copy. Missense variants: 753 observed, 910.75 expected, observed/expected ratio (o/e) 0.83, 90% interval 0.78 to 0.88. Synonymous variants: 384 observed, 362.82 expected, observed/expected ratio (o/e) 1.06, 90% interval 0.97 to 1.15.
Homologues: Orthologues: chimpanzee TBC1D14 (99% identical), macaque TBC1D14 (99% identical), rat Tbc1d14 (91% identical), mouse Tbc1d14 (91% identical), guinea pig TBC1D14 (87% identical), rabbit TBC1D14 (86% identical), tropical clawed frog tbc1d14 (69% identical), zebrafish tbc1d14 (63% identical). Paralogues in human: TBC1D12 (50% identical), RABGAP1L (17% identical), RABGAP1 (16% identical), USP6NL (16% identical), TBC1D4 (15% identical), TBC1D1 (15% identical), TBCK (15% identical), TBC1D10B (15% identical), TBC1D2 (15% identical), TBC1D2B (15% identical), TBC1D9 (14% identical), TBC1D9B (14% identical), and 33 more.
Diseases named in the same sentence as TBC1D14 in open-access papers:
TBC1D14 is named in the same sentence as 10 diseases in open-access papers, as found by Europe PMC text mining. Sharing a sentence is not in itself a finding about the gene and the disease. The quoted sentences say what the papers report.
head and neck squamous cell carcinoma (2 papers, 2022 to 2023). A squamous cell carcinoma that arises from any of the following anatomic sites: lip and oral cavity, nasal cavity, paranasal sinuses, pharynx, larynx, and salivary glands. "TBC1D14 was found to inhibit lymph node metastasis by regulating autophagy in head and neck squamous cell carcinoma." (PMID 36930369, 2023).
cancer (4 papers, 2015 to 2024). A tumor composed of atypical neoplastic, often pleomorphic cells that invade other tissues. "The results showed that the mRNA levels of TBC1D1, TBC1D7, TBC1D8 and TBC1D14 significantly varied between different cancer stages, whereas the mRNA levels of TBC1D9b and TBC1D25 did not." (PMID 38766486, 2024). "Previous studies have revealed the roles of TBC1D8 and TBC1D14 in other types of cancers, so these two TBC1Ds were knocked out in Hep3B cells in this study." (PMID 38766486, 2024). "Previous studies on TBC1D14 (parental gene of novel_circ_0010160) demonstrated its important role in cancer cell autophagy." (PMID 36425117, 2022). "To further investigate the role of TBC1Ds on the malignant feature of HCC, we knockout the expression of TBC1D8 and TBC1D14 in Hep3B cells as these two genes play vital function in other types of cancers and showed relative tighter relationship to the prognosis of patients with HCC." (PMID 38766486, 2024). "Moreover, the expression level of TBC1D14 was significantly correlated with HCC cancer stage." (PMID 38766486, 2024). "Therefore, the correlation between TBC1D14 expression and autophagy in cancer cells without starvation induction seems plausible." (PMID 35342354, 2022). "The functions of TBC1D9b, TBC1D14 and TBC1D25 in cancer have not been well studied but are known to be closely related to autophagy." (PMID 38766486, 2024).
tumor (3 papers, 2022 to 2025). "In order to address the impact of TBC1D14 expression on tumor cell behavior at the mechanistic level, the stable overexpression or downregulation of LV-mediated TBC1D14 was established with HNSCC cell lines FaDu and SCC15." (PMID 35342354, 2022). "Despite several recent studies reporting members of the TBC1 domain family as tumor suppressors in breast cancer and epithelial ovarian cancer 18-21, the exact role of TBC1D14 in HNSCC remains poorly understood." (PMID 35342354, 2022). "In the present study, TBC1D9b, TBC1D14 and TBC1D25 were significantly overexpressed in HCC, and the expression levels of TBC1D9b, TBC1D14 and TBC1D25 were significantly correlated with HCC tumor grade." (PMID 38766486, 2024). "The body weight of mice did not significantly change within 40 days (data not shown), but tumor volume, LN volume, and LN weight were lower in the TBC1D14 overexpression group than in the empty vector group." (PMID 35342354, 2022). "However, the role of TBC1D14 in tumor cells has not yet been elucidated." (PMID 35342354, 2022).
TBC1D14 also shares sentences with these, for which no sentence is quoted: adenovirus infection (1 paper); asthma (1); atherosclerosis (1); childhood asthma (1); gastric cancer (1); lymph node metastasis (1); skin cutaneous melanoma (1).